CNPY1 (canopy FGF signaling regulator 1)
Tractability: No criterion of Open Targets' tractability assessment is met for any kind of drug.
Gene: Protein-coding gene on chromosome 7 (155,474,206 to 155,555,450, reverse strand). Ensembl gene ENSG00000146910.
Genetic constraint (gnomAD): Loss-of-function variants: 8 observed, 6.65 expected, observed/expected ratio (o/e) 1.2, 90% interval 0.69 to 1.86. That is too few expected variants to judge how well the gene tolerates losing a copy. Missense variants: 74 observed, 78.94 expected, observed/expected ratio (o/e) 0.94, 90% interval 0.78 to 1.14. Synonymous variants: 23 observed, 29.42 expected, observed/expected ratio (o/e) 0.78, 90% interval 0.56 to 1.11.
Homologues: Orthologues: chimpanzee CNPY1 (98% identical), dog CNPY1 (86% identical), rat Cnpy1 (77% identical), mouse Cnpy1 (75% identical), macaque CNPY1 (72% identical), chimpanzee CNPY1 (62% identical), tropical clawed frog cnpy1 (50% identical), zebrafish cnpy1 (50% identical), Drosophila melanogaster sel (27% identical), Caenorhabditis elegans F01F1.15 (25% identical), Caenorhabditis elegans F01F1.11 (21% identical), Caenorhabditis elegans Y47H9C.8 (18% identical). Paralogues in human: CNPY2 (43% identical).
Diseases named in the same sentence as CNPY1 in open-access papers:
CNPY1 is named in the same sentence as 5 diseases in open-access papers, as found by Europe PMC text mining. Sharing a sentence is not in itself a finding about the gene and the disease. The quoted sentences say what the papers report.
autism (1 paper, 2025). Persistent deficits in social interaction and communication and interaction as well as a markedly restricted repertoire of activity and interest as well as repetitive patterns of behavior. "SNP rs11769197 was mapped to CNPY1, which has been reported to have associations with autism, schizophrenia, urate measurement, COVID-19, and bone density." (PMID 40011956, 2025).
diabetic nephropathy (1 paper, 2019). "Overexpression of miR‐370 was shown to promote mesangial cell proliferation and extracellular matrix accumulation by suppressing CNPY1 in a rat model of diabetic nephropathy." (PMID 30950172, 2019).
CNPY1 also shares sentences with these, for which no sentence is quoted: COVID-19 (1 paper); lymphoblastic leukemia (1); schizophrenia (1).